B4GALNT4 (beta-1,4-N-acetyl-galactosaminyltransferase 4)
Description:
Transfers N-acetylgalactosamine (GalNAc) from UDP-GalNAc to N-acetylglucosamine-beta-benzyl with a beta-1,4-linkage to form N,N'-diacetyllactosediamine, GalNAc-beta-1,4-GlcNAc structures in N-linked glycans and probably O-linked glycans.
Synonyms: NGalNAc-T1; FLJ25045
Tractability: Antibody: UniProt predicts a signal peptide or a membrane-spanning region. PROTAC: ubiquitination databases record sites on it.
Gene: Protein-coding gene on chromosome 11 (369,457 to 382,117, forward strand). Ensembl gene ENSG00000182272.
Subcellular location: Golgi apparatus, Golgi stack membrane
Subcellular location (Human Protein Atlas): Cytosol; Nucleoplasm; Vesicles
Gene Ontology:
Molecular function: acetylgalactosaminyltransferase activity; N-acetyl-beta-glucosaminyl-derivative 4-beta-N-acetylgalactosaminyltransferase activity
Cellular component: Golgi cisterna membrane
Genetic constraint (gnomAD): Loss-of-function variants: 77 observed, 87.87 expected, observed/expected ratio (o/e) 0.88, 90% interval 0.73 to 1.06. The synonymous counts are far from expectation, so gnomAD's model fits this gene poorly and the ratio says little. Missense variants: 1,554 observed, 1,282.6 expected, observed/expected ratio (o/e) 1.21, 90% interval 1.16 to 1.26. Synonymous variants: 772 observed, 546.88 expected, observed/expected ratio (o/e) 1.41, 90% interval 1.33 to 1.5.
Homologues: Orthologues: chimpanzee B4GALNT4 (99% identical), macaque B4GALNT4 (94% identical), pig B4GALNT4 (87% identical), dog B4GALNT4 (86% identical), rat B4galnt4 (85% identical), mouse B4galnt4 (85% identical), guinea pig B4GALNT4 (76% identical), zebrafish b4galnt4a (56% identical), tropical clawed frog b4galnt4 (56% identical), zebrafish b4galnt4b (53% identical). Paralogues in human: B4GALNT3 (43% identical), CHSY1 (14% identical), CHSY3 (14% identical), CHPF2 (13% identical), CHPF (11% identical), CSGALNACT2 (10% identical), CSGALNACT1 (10% identical).
Diseases named in the same sentence as B4GALNT4 in open-access papers:
B4GALNT4 is named in the same sentence as 10 diseases in open-access papers, as found by Europe PMC text mining. Sharing a sentence is not in itself a finding about the gene and the disease. The quoted sentences say what the papers report.
prostate carcinoma (5 papers, 2019 to 2026). A carcinoma that arises from epithelial cells of the prostate gland. "Furthermore, authors revealed such genes for the TMPRSS2-ERG prostate cancer molecular subtype (B4GALNT4, ASRGL1, MYBPC1, RGS11, SLC6A14, GALNT13 and ST6GALNAC1)." (PMID 36077746, 2022). "Additionally, we revealed such genes for the TMPRSS2-ERG prostate cancer molecular subtype (B4GALNT4, ASRGL1, MYBPC1, RGS11, SLC6A14, GALNT13, and ST6GALNAC1)." (PMID 31447885, 2019). "In addition, most of the model genes showed varying degrees of downregulation in the presence of Cu2+ and Elesclomol in most PCa cell lines, with B4GALNT4 and FAM83D being the most significant (p<0.05), demonstrating the close association of these two genes with cuproptosis in prostate cancer cells." (PMID 37205181, 2023). "Additionally, while CDC20, COL1A2 and S100A10 possess recognized pro-oncogenic activities, the precise roles of B4GALNT4 and NUAK1 in prostate cancer warrant elucidation." (PMID 39391236, 2024).
ovarian carcinoma (2 papers, 2017 to 2023). A malignant neoplasm originating from the surface ovarian epithelium. "COL18A1 and B4GALNT4 are also overexpressed in endometrial and ovarian cancers according to the HPA and are unfavorable markers for overall survival for both cancers." (PMID 37775701, 2023). "Interestingly, two of the four possible β1‐4‐acetylgalactosamine transferase genes (B4GALNT1‐4), B4GALNT3 and B4GALNT4, were found to be significantly elevated (P < 0.05) in the ovarian cancer tissues as compared to the peritoneum." (PMID 28853212, 2017).
esophageal squamous cell carcinoma (1 paper, 2022). Esophageal squamous cell carcinoma (ESCC) is a type of esophageal carcinoma (EC) that can affect any part of the esophagus, but is usually located in the upper or middle third. "B4GALNT4 is linked to malignant behavior and maybe a new prognostic marker for esophageal squamous cell carcinoma." (PMID 36439479, 2022).
Obesity (1 paper, 2025). Accumulation of substantial excess body fat. "In male offspring, associated dmCpGs were linked to known obesity-related genes including B4GALNT4 (cg25020933, cg15762098), ADCY9 (insulin secretion and thyroid hormone synthesis) (cg00610508), ADRB1 (cg13848598) and ATP10D (cg14009629)." (PMID 40410506, 2025).
serous ovarian cancers (1 paper, 2017). "The MS profiling by PGC‐LC also revealed several glycan structural isomers that corresponded to LacdiNAc‐type (GalNAcβ1‐4GlcNAc) motifs that were unique to the serous ovarian cancers and that correlated with elevated gene expression of B4GALNT3 and B4GALNT4 in patients with serous cancer." (PMID 28853212, 2017).
viral infections (1 paper, 2021). "If further research supports our suggestion that B4GALNT4 is involved in the viral immune response in mallards, this gene is a good candidate for future functional studies with potential to improve our understanding of how mallards clear viral infections." (PMID 34031452, 2021).
cancer (3 papers, 2023 to 2024). A tumor composed of atypical neoplastic, often pleomorphic cells that invade other tissues. "B4GALNT4 is upregulated in various cancers, and its expression can enhance the malignant potential of cancers." (PMID 37205181, 2023). "Additionally, GSEA analysis revealed that multiple cancer-related pathways were inhibited after the knockdown of B4GALNT4, including the PI3K−Akt signaling pathway, Rap1 signaling pathway, and Wnt signaling pathway." (PMID 37205181, 2023). "Meanwhile, transcriptomics analysis suggested that the knockdown of B4GALNT4 inhibited several classical pro-cancer pathways, including PI3K−Akt signaling and Wnt signaling pathways, indicating a pro-carcinogenic role of B4GALNT4 in PCa." (PMID 37205181, 2023).
tumor (2 papers, 2017 to 2026). "Moreover, B4GALNT4 knockdown suppresses tumor growth in xenograft models and correlates with decreased PDK1 and p-AKT levels in vivo." (PMID 41698153, 2026).
B4GALNT4 also shares sentences with these, for which no sentence is quoted: autism (1 paper); peritoneal cancer (1).